HSDL2 (hydroxysteroid dehydrogenase like 2)
Diseases named in the same sentence as HSDL2 in open-access papers (continued):
Sharing a sentence is not in itself a finding about the gene and the disease.
melanoma (1 paper, 2022). A malignant, usually aggressive tumor composed of atypical, neoplastic melanocytes. "Importantly, Kaplan–Meier survival curve analysis demonstrated that there was a marked association between higher expression of HSDL2 and worse melanoma patient survival." (PMID 35193614, 2022). "Taken together, these in vitro and in vivo results suggested that HSDL2 promotes melanoma cell proliferation and inhibits melanoma cell apoptosis." (PMID 35193614, 2022). "HSDL2 is overexpressed in melanoma and promotes melanoma progression by activating the ERK and AKT pathways." (PMID 35193614, 2022). "Our results showed that CuE effectively suppressed the growth of melanoma cells and inhibited the expression of HSDL2." (PMID 35193614, 2022). "Since HSDL2 had a positive effect on melanoma growth, we attempted to identify a regulator of HSDL2 expression." (PMID 35193614, 2022). "HSDL2 was upregulated in melanoma, which was confirmed by the higher rate of immunopositivity relative to nontumour tissue." (PMID 35193614, 2022). "Our data demonstrated that HSDL2 is overexpressed in melanoma tissues and that its silencing blocks melanoma progression by inhibiting cell proliferation and enhancing apoptosis via inhibition of the ERK and AKT pathways." (PMID 35193614, 2022). "Therefore, our results provide the first evidence of a causal relationship between HSDL2 expression and the ERK and Akt signalling pathways in human melanoma development." (PMID 35193614, 2022). "HSDL2 expression was examined in melanoma and adjacent normal tissues by immunohistochemistry." (PMID 35193614, 2022). "In vitro and in vivo experiments revealed that HSDL2 is important for melanoma growth." (PMID 35193614, 2022). "To investigate the molecular basis for the effects of HSDL2 on melanoma cell proliferation and survival, we examined the activation status of multiple intracellular signalling proteins involved in cell survival and proliferation using stress, apoptosis, and RTK signalling arrays." (PMID 35193614, 2022). "CuE could inhibit the ERK and AKT pathways by decreasing HSDL2 expression; therefore, CuE could inhibit melanoma growth in vitro and in vivo." (PMID 35193614, 2022). "HSDL2 may be a promising therapeutic target against melanoma, and CuE can inhibit melanoma by downregulating HSDL2 expression." (PMID 35193614, 2022). "Some natural compounds that could inhibit the expression of HSDL2 to slow melanoma progression would provide new prospects and methods for the treatment of patients with melanomas." (PMID 35193614, 2022). "Our results suggest that CuE may be a useful chemopreventive strategy for melanoma patients with high HSDL2 levels." (PMID 35193614, 2022). "Our data show that HSDL2 is overexpressed in melanoma relative to adjacent normal tissue." (PMID 35193614, 2022). "Combined with HSDL2 knockdown and overexpression assays in melanoma cells, the data confirmed the positive role of HSDL2 in melanoma proliferation and apoptotic inhibition, suggesting that silencing HSDL2 may be a potential strategy for blocking melanoma progression." (PMID 35193614, 2022). "Fortunately, our data demonstrated that CuE could inhibit HSDL2 expression and melanoma cell proliferation and induce cell apoptosis, a significant target for slowing tumour development, by suppressing the ERK and AKT pathways and reducing xenograft melanoma growth." (PMID 35193614, 2022). "Moreover, CuE inhibited melanoma growth by blocking the HSDL2-mediated ERK and AKT pathways." (PMID 35193614, 2022). "However, little is known about the expression and function(s) of HSDL2 in melanoma." (PMID 35193614, 2022). "However, to date, the function of HSDL2 in melanoma remains unclear." (PMID 35193614, 2022). "Therefore, HSDL2 may be a promising therapeutic target against melanoma." (PMID 35193614, 2022).
melanoma (continued). "In this paper, we found that HSDL2 promoted cell proliferation and suppressed apoptotic cell death by activating the AKT and ERK signalling pathways and that CuE could slow melanoma growth by inhibiting the AKT and ERK signalling pathways via the downregulation of HSDL2 expression." (PMID 35193614, 2022).
pancreatic cancer (1 paper, 2022). "HSDL2 was highly expressed in pancreatic cancer and connected with shorter overall survival, meanwhile proliferation and lipid metabolism were further inhibited when HSDL2 was silenced in pancreatic cancer cell." (PMID 35948893, 2022).
type 1 diabetes (1 paper, 2024). "The expression of hepatic CYP8B1 is regulated exactly as HSDL2: It is (i) increased upon fasting, (ii) activated by PPARα agonists, (iii) repressed by insulin, and (iv) elevated in type 1 diabetes." (PMID 38820148, 2024). "Previous studies have shown that conditions such as fasting, PPARα stimulation, and type 1 diabetes, which we found to promote HSDL2 expression, often associate with alterations in BA pool composition rather than total BA levels." (PMID 38820148, 2024).
tumor (9 papers, 2019 to 2024). "In our study, K1 cells exert BRAF mutation, the tumor-promoting role of HSDL2 gene, or its interaction network in PTC presenting BRAF-wt remained poorly known." (PMID 31101684, 2019). "In these reports, elevated HSDL2 was often linked to tumor grade and poor overall survival." (PMID 38820148, 2024). "Much smaller tumours were formed by HSDL2-depleted A375 cells, and the average tumour weight and volume at the end of the experiment were markedly decreased in HSDL2-depleted cells relative to control cells." (PMID 35193614, 2022). "Studies have shown that the role of HSDL2 in tumor progression is complex and influenced by the type of tumor." (PMID 32211805, 2020). "Several previous studies investigating the effects of HSDL2 in other malignant tumors have also confirmed the anti-tumor effects of HSDL2 KD." (PMID 32211805, 2020). "Their results from in vivo experiments showed that HSDL2 KD significantly suppressed the tumor growth." (PMID 32211805, 2020). "Bioinformatics analyses suggested that various genes were involved in the interaction network of tumor-promoting role of HSDL2 gene in PTC." (PMID 31101684, 2019). "HSDL2 is localized to peroxisomes and affects tumor progression by modulating lipid metabolism." (PMID 37718459, 2023). "HSDL2 expression is dysregulated in various cancers and is correlated with tumor progression." (PMID 37718459, 2023). "Moreover, in the subcutaneous tumour xenografting assay, upregulation of HSDL2 promoted tumour growth, and the overexpression of HSDL2 slowed the antitumour activity of CuE." (PMID 35193614, 2022). "Finally, a subcutaneous tumour xenografting assay in BALB/c nude mice demonstrated that stably silencing HSDL2 in A375 cells significantly suppressed tumour growth." (PMID 35193614, 2022). "This suggests that HSDL2 is involved not only in tumorigenesis but also in tumour progression." (PMID 35193614, 2022). "Hence, our group intended to find the answer about if HSDL2 involves tumour progression by regulating lipid metabolism." (PMID 33738911, 2021). "We hypothesized that HSDL2 has different targets in different tumors, or that these genes are all targets of HSDL2 and are involved in regulating tumor progression together." (PMID 32211805, 2020). "But unfortunately, the molecular mechanism underlying the role of HSDL2 on tumor progression has not been further explored in these studies." (PMID 32211805, 2020). "Based on the results from microarray hybridization and gene expression analysis, we speculated that protein kinase B β (AKT2) is a downstream protein of HSDL2, which plays an important role in the anti-tumor process induced by HSDL2 KD." (PMID 32211805, 2020). "Furthermore, mice injected with HSDL2-knockdown K1 cells had smaller tumor size, volume and weight than those receiving shCtrl." (PMID 31101684, 2019). "Second, we found that the expression levels of HSDL2 in PTC tissue and cell specimens were significantly increased, and that HSDL2 knockdown could inhibit tumor growth." (PMID 31101684, 2019). "Inhibiting the expression of HSDL2 gene could obviously reduce tumor weights and sizes in animal models (P<0.05)." (PMID 31101684, 2019). "Tumor promoting pathway induced by HSDL2 in B-CPAP cells might be inhibited." (PMID 31101684, 2019). "The functions of HSDL2 in PTC might be distinct in different types of tumor cells." (PMID 31101684, 2019). "In vivo, the knockdown of HSDL2 gene could significantly suppress tumor growth (all P<0.05)." (PMID 31101684, 2019). "HSDL2 was markedly downregulated in CCA patients with a high number of tumors, large tumor size, vascular invasion, and low total cholesterol levels compared to CCA patients with other features." (PMID 37718459, 2023).
tumor (continued). "Thus, it is reasonable to hypothesize that HSDL2 might be involved in tumor progression." (PMID 31101684, 2019). "There were no changes in the average weight or volume of tumours between HSDL2-overexpressing cells treated with CuE and cells treated with CuE alone." (PMID 35193614, 2022). "HSDL2 expression was increased in PTC tissues and cells, which could promote tumor progression in vitro and in vivo." (PMID 31101684, 2019). "Knockdown of HSDL2 gene could suppress cell proliferation and promote cell apoptosis for PTC cells, thus inhibiting tumor growth in vivo." (PMID 31101684, 2019).
cancer (8 papers, 2019 to 2024). A tumor composed of atypical neoplastic, often pleomorphic cells that invade other tissues. "It is possible that some cancer cell lines might have developed a dependency to HSDL2, rendering them particularly sensitive to its loss." (PMID 38820148, 2024). "Recent studies have shown that HSDL2 levels are high in several human cancers including brain, ovarian, breast, bladder, thyroid, lung, pancreas, and cervix." (PMID 38820148, 2024). "Previous studies reported that HSDL2 levels are high in several cancers and that repressing HSDL2 impairs proliferation and survival." (PMID 38820148, 2024). "Lower expression of lipogenic regulators and reduced triglyceride accumulation were also measured in some cancer cell lines upon HSDL2 knockdown." (PMID 38820148, 2024). "As a new member of the steroid dehydrogenase family, HSDL2 is considered to be involved in lipid metabolism, and the occurrence, proliferation, development of cancer cells." (PMID 35053111, 2022). "The outcome above reminded us that HSDL2 functions as the momentous factor in altered lipid metabolism promoting cancer progress." (PMID 33738911, 2021). "There was a statistically significant difference in the expression of HSDL2 between cancer tissues and adjacent tissues (P<0.001)." (PMID 32211805, 2020). "We previously analyzed CCA microarray datasets from the Gene Expression Omnibus database (three datasets with a total of 353 samples) and The Cancer Genome Atlas (clinical samples of 45 patients) and found that HSDL2 expression was markedly lower in CCA tissues than in matched peritumoral tissues." (PMID 37718459, 2023). "Therefore, recent studies have paid more attention to the lipid metabolism of HSDL2 in various cancers." (PMID 36675957, 2022). "Patients with high HSDL2 expression in cancer tissues had a worse overall survival (P<0.001)." (PMID 32211805, 2020). "In 86 cancer tissues, HSDL2 was highly expressed in 63 (73.3%) tissues." (PMID 32211805, 2020). "In addition, survival analysis showed that patients with high HSDL2 expression in cancer tissues had a worse overall survival (P<0.001)." (PMID 32211805, 2020). "HSDL2 promoted PTC progression which could be employed as a novel therapeutic target for the cancer." (PMID 31101684, 2019). "HSDL2, a member of SDRs super family, which could be found in peroxisomes and mitochondria, was indicated in growing body of literature about the vital role in the cancer progression." (PMID 33738911, 2021). "HSDL2 might play diverse roles in different types of cancer." (PMID 31101684, 2019). "Human hydroxysteroid dehydrogenase-like 2 (HSDL2), which regulates cancer progression, is involved in lipid metabolism." (PMID 37718459, 2023). "Based on the information that EMT is the key of cell behaviour and pathologically contributes to the progression of cancers, we applied western blotting assay to determine the correlation between EMT and expression of HSDL2." (PMID 33738911, 2021). "The mechanism linking HSDL2 to cancer cell survival was not clearly demonstrated in these reports." (PMID 38820148, 2024).
HSDL2 also shares sentences with these, for which no sentence is quoted: cognitive decline (1 paper); Epileptic Seizures (1); glioblastoma (1); heart failure (1); infection (1); Obesity (1); thyroid carcinoma (1).